PCSK9 (proprotein convertase subtilisin/kexin type 9)
Diseases named in the same sentence as PCSK9 in open-access papers (continued):
Sharing a sentence is not in itself a finding about the gene and the disease.
Hypercholesterolemia (continued). "During all the mechanisms that regulate the dyslipidemia, PCSK9 inhibition has been verified as a biological target in enhancing serum cholesterol clearance, companying with improving the hypercholesterolemia of obese patients." (PMID 37935689, 2023). "Based on our findings, treatment with PCSK9 inhibitors for hypercholesterolemia offers an additional benefit of lowering Lp(a) levels." (PMID 37834124, 2023). "Despite available data about the beneficial effects of PCSK9 inhibitor antibodies in cardiovascular diseases and hypercholesterolemia, specific data about PCSK9 metabolism and the effects of PCSK9 inhibitors on cardiovascular health in elderly are limited." (PMID 38094682, 2023). "Demonstrating effectiveness in studies addressing myocardial infarction and hypercholesterolaemia, drugs that target PCSK9 hold substantial promise for treating atherosclerosis, hypercholesterolaemia, and other related cardiovascular diseases." (PMID 38144368, 2023). "It appears that anti-PCSK9 therapy not only improves hypercholesterolemia but also treats steatohepatitis." (PMID 37466835, 2023). "Discovery of the mechanism has resulted in the development of pharmacological applications and nowadays PCSK9 inhibitors are a common treatment for hypercholesterolemia." (PMID 37642746, 2023). "Proprotein convertase subtilisin kexin 9 (PCSK9) has attracted attention as a therapeutic target for patients with hypercholesterolemia due to its ability to reduce low-density lipoprotein cholesterol (LDL-C) levels." (PMID 37892538, 2023). "In the present work, we propose a model-informed approach for the optimization of MACE endpoint, based on a model-based meta-analysis of anti-hypercholesterolemia trials involving statin and anti-PCSK9 drugs." (PMID 38304061, 2023). "In general, new technologies based on gene editing are a potential for clinical applications in the future, including, in particular, PCSK9 targeting for hypercholesterolemia management." (PMID 36831039, 2023). "Inhibition of PCSK9 has emerged as a novel therapy to treat hypercholesterolemia and related cardiovascular diseases." (PMID 36900189, 2023). "PCSK9 control mice (PCSK9-WT) develop hypercholesterolemia and spontaneous atherosclerosis, as recently described by our group." (PMID 37701434, 2023). "The FOURIER study and ODYSSEY study have also established the PCSK9 antibody’s position in the therapy of hypercholesterolemia and prevention of atherosclerotic coronary artery disease (ASCVD) and stroke." (PMID 37005689, 2023). "The role of PCSK9 as a regulator of LDLRs and in development of hypercholesterolemia is well described and overexpression of PCSK9 accumulates LDL in the circulation." (PMID 37642746, 2023). "In recent years, PCSK9 has been selected as a target to be therapeutically inhibited in hypercholesterolemia." (PMID 39086674, 2023). "GalNAc-LNPs were formulated with an adenine base editor 8.8-m (ABE8.8) mRNA and a guide RNA (gRNA) targeting the mouse Angptl3 or Pcsk9 genes—well-validated therapeutic targets for the treatment of hypercholesterolemia." (PMID 37188660, 2023). "Type 2 diabetes patients on medication and those with PCSK9 (proprotein convertase subtilisin/kexin type 9) rs151193009 had low odds for hypercholesterolemia." (PMID 36980993, 2023).
Hypercholesterolemia (continued). "It is a major point of control in cholesterol homeostasis and HMGCR and PCSK9 inhibitors have been widely used to treat hypercholesterolemia in clinical settings." (PMID 36782330, 2023). "In a separate carotid ligation mouse model, PCSK9 overexpression using AAV-PCSK9 led to elevated serum PCSK9, hypercholesterolemia and rapid atherosclerosis development within 3 weeks when compared to the control." (PMID 37371118, 2023). "Recent research confirms that an increase in circulating PCSK9 levels not only accompanies hypercholesterolemia but also leads to higher glucose levels, insulin resistance, and T2DM." (PMID 38028979, 2023). "Familial hypercholesterolemia causes extremely high circulating LDL-C levels, which are due to mutations of different genes involved in LDL-C metabolism, such as PCSK9." (PMID 36834701, 2023). "Another mechanism by which PCSK9 can modulate the migration of monocytes is the chemokine receptor type-2, which was inhibited by PCSK9 inhibitors in patients with familial hypercholesterolemia and decreased the capacity of monocytes to pass the endothelium." (PMID 37765005, 2023). "Platelet activation, soluble Nox2-derivated peptide, and oxidised LDL were monitored in patients with familial hypercholesterolemia before, and after, treatment with PCSK9 inhibitors." (PMID 37765005, 2023). "Marketed PCSK9 mAb inhibitors evolocumab and alirocumab are currently being used for the treatment of homozygous familial hypercholesterolemia proving the therapeutic potential of targeting PCSK9." (PMID 36771126, 2023). "Gain-of-function mutations in the PCSK9 gene result in increased blood PCSK9 protein levels, LDL receptor degradation, and increased blood LDL-C, which causes familial hypercholesterolemia." (PMID 37012310, 2023). "A liver function test has been done in patients with familial hypercholesterolemia taking PCSK9 inhibitors." (PMID 36655117, 2023). "According to keyword analysis, “low density lipoprotein”, “familial hypercholesterolemia”, “PCSK9 inhibitor”, “PCSK9”, and “efficacy” are the five keywords with the highest frequency of co-occurrence." (PMID 38093957, 2023). "Genes involved in familial hypercholesterolemia are low density lipoprotein receptor gene, apolipoprotein B, proprotein convertase subtilisin/kexin type 9, low density lipoprotein receptor adapter protein 1, other unidentified genes." (PMID 38125244, 2023).
Hypercholesterolemia (continued). "PCSK9-inhibitory drugs, like alirocumab and evolocumab, have been approved for trapping circulating PCSK9 for treatment of hypercholesterolemia." (PMID 36242053, 2022). "Up to now, only two anti-PCSK9 monoclonal antibodies, namely evolocumab and alirocumab, have received approval on the hypercholesterolemia treatment from the United States Food and Drug Administration and the European Union." (PMID 35571202, 2022). "The purpose of this trial was to determine the efficacy of PCSK9 inhibitors alone in patients with isolated hypercholesterolemia." (PMID 35566668, 2022). "New other gene-editing technologies targeting PCSK9 are becoming promising tools for the management of hypercholesterolemia." (PMID 36232746, 2022). "Our results demonstrate that Nar administration can reduce PCSK9 levels, opening a new scenery to the pharmacological intervention on hypercholesterolemia." (PMID 36555447, 2022). "Our findings reveal that Dennd5b−/− mice are resistant to PCSK9-induced hypercholesterolemia and atherosclerosis." (PMID 36243100, 2022). "PCSK9 has since been clinically validated as a therapeutic target for the treatment of hypercholesterolemia and atherosclerosis." (PMID 36209894, 2022). "Anti-PCSK9 antibodies, alirocumab and evolocumab are monoclonal antibodies approved for clinical use in the treatment of hypercholesterolemia." (PMID 35893294, 2022). "PCSK9 inhibition reduces fractions 5–11 in hypercholesterolemia and 1–11 in mixed hyperlipidemia and FDBL." (PMID 35320320, 2022). "In the early 2000s, ezetimibe was approved for hypercholesterolemia and then PCSK9 inhibitors with a well-documented safety and efficacy profile." (PMID 36348882, 2022). "Compared to Dennd5b+/+ mice, Dennd5b−/− mice were resistant to diet-induced weight gain and PCSK9-induced hypercholesterolemia." (PMID 36243100, 2022). "miR-483-5p associates with obesity and cardiovascular disease, also ameliorates hypercholesterolemia by inhibiting PCSK9 production." (PMID 35152894, 2022). "Although numerous studies have addressed the role of PCSK9 role in controlling hypercholesterolemia, studies and discussions exploring its involvement in platelet activation are still limited." (PMID 35207479, 2022). "Given the functional diversity of PCSK9, it has been considered to be a new prognostic factor for cardiovascular events in high-risk populations including CAD and family hypercholesterolemia." (PMID 34996457, 2022). "In cardiovascular disease research, the porcine atherosclerosis model has also been used to examine the molecular activities of PCSK9 as an anti-hypercholesterolemia medication." (PMID 36005422, 2022). "The future of evinacumab seems to be slightly different from that of other drugs intended for severe hypercholesterolemia, such as PCSK9 inhibitors (alirocumab, evolocumab) and inclisiran." (PMID 36614969, 2022). "Due to this correlation, peripheral PCSK9 inhibition with monoclonal antibodies is an established therapy to reduce the plasma cholesterol level in patients suffering from hypercholesterolemia by increasing the LDL receptor density at the cell surface." (PMID 35344086, 2022). "In the present study, with the use of adeno-associated virus (AAV)-PCSK9 and TRPM2 knockout (TRPM2−/−) mice, we determined the role of TRPM2 in hypercholesterolemia-induced atherosclerosis." (PMID 35563730, 2022). "The major reason is that there are only two monoclonal antibodies targeting PCSK9 available for treating hypercholesterolemia in clinic." (PMID 35832650, 2022).
Hypercholesterolemia (continued). "Previous studies have found a correlation between plasma PCSK9 and platelet reactivity in patients with coronary artery disease and hypercholesterolemia." (PMID 36324757, 2022). "MAB-based PCSK9 inhibitors such as alirocumab and evolocumab have been approved for use in hypercholesterolemia in combination with statins." (PMID 35795514, 2022). "In contrast, studies on loss-of-function mutations in PCSK9 indicate that inactivation of PCSK9 lowers LDL-C levels and reduces CHD, suggesting PCSK9 inhibition as a valid therapeutic method in the management of hypercholesterolemia and related diseases." (PMID 35935390, 2022). "Elevated LDL levels in familial hypercholesterolemia are linked to three single genetic mutations: LDL receptors, proprotein convertase subtilisin/kexin type 9 (PCSK9), and apolipoprotein (Apo) B." (PMID 35135581, 2022). "The importance of the proprotein convertase subtilisin/kexin type-9 (PCSK9) gene was quickly recognized by the scientific community as the third locus for familial hypercholesterolemia." (PMID 35323658, 2022). "PCSK9 mAbs was found to be effective in improvement of sexual dysfunction in male with familial hypercholesterolemia." (PMID 35323699, 2022). "Evolocumab, a neutralizing antibody to human PCSK9, has been tested in clinical trials for familial hypercholesterolemia or hyperlipidemia that cannot be controlled by statins." (PMID 35720337, 2022). "Numerous PCSK9 mutations have been identified in all three domains that confer a gain-of-function (GOF), resulting in an autosomal-dominant form of familial hypercholesterolemia (FH)." (PMID 36187800, 2022). "As a secretory protein and third locus of familial hypercholesterolemia, the majority of reports have focused on the role of circulating PCSK9 in the context of CVD." (PMID 35323658, 2022). "Monoclonal anti-PCSK9 neutralizing antibodies are currently used for a potent reduction of the LDLc levels by 50–60% and are indicated for patients with familial hypercholesterolemia or those who are statin-intolerant who need cardiovascular prevention." (PMID 35130916, 2022). "In recent years, PCSK9 is one of the promising hot targets in the field of cardiovascular research, and the PCSK9 antibody has been used to treat some patients with familial hypercholesterolemia and statin tolerance." (PMID 35733117, 2022). "Studies confirm improvements in arterial stiffness during therapy with PCSK9 inhibitors in patients with familial hypercholesterolemia." (PMID 35323699, 2022). "Nevertheless, experts believe that use of PCSK9 inhibitors is still beneficial for COVID-19 patients with familial hypercholesterolemia." (PMID 35918332, 2022). "The model was tested for its ability to mimic known biochemical effects of familial hypercholesterolemia, statin therapy, and PCSK9 inhibitors." (PMID 35657919, 2022). "A positive correlation between plasma PCSK9 levels and carotid calcifications has also been demonstrated by CT scans in patients with familial hypercholesterolemia." (PMID 35354429, 2022).
Hypercholesterolemia (continued). "On the contrary, PCSK9 is a new target for the prevention and treatment of hypercholesterolemia, which has been only rarely investigated in the area of food bioactive peptides." (PMID 33808034, 2021). "This real-world data analysis evaluated data from patients in a tertiary center who received PCSK9 inhibitors for the treatment of hypercholesterolemia." (PMID 33894772, 2021). "Our data indicate that h5E12-L230G is a high-affinity anti-PCSK9 antibody candidate with an extremely slow dissociation rate for favorably treating hypercholesterolemia and relevant cardiovascular diseases." (PMID 34944600, 2021). "Our data show that 3 weeks of AAV-mediated expression of murine PCSK9-D377Y in male C57BL/6N mice produces hypercholesterolemia." (PMID 34631822, 2021). "AT04A and AT06A are two AFFITOPE® peptide vaccine candidates being developed for the treatment of hypercholesterolemia by inducing proprotein convertase subtilisin/kexin type 9 (PCSK9)-specific antibodies." (PMID 33969434, 2021). "These mutations led to the development of proprotein convertase subtilisin/kexin type 9 (PCSK9) inhibitors, which are currently used to treat statin-resistant hypercholesterolemia." (PMID 33926499, 2021). "The recent 2019 European guidelines for the management of hypercholesterolemia have added PCSK9 inhibitors to the therapeutic armamentarium to achieve the LDL-C goals." (PMID 33694108, 2021). "Proprotein convertase subtilisin kexin 9 (PCSK9) has lately received considerable attention as a target for the reduction of LDL-C levels in patients with hypercholesterolemia." (PMID 34070931, 2021). "In the early 2000s, ezetimibe was approved for hypercholesterolemia, followed by PCSK9 inhibitors several years later, and BDA more recently." (PMID 34869702, 2021). "A phase 3 trial that compares the PCSK9 inhibitor evolocumab to LDL apheresis in patients with hypercholesterolemia has been completed (NCT03429998)." (PMID 34442464, 2021). "PCSK9 inhibitors, another add-on therapy for hypercholesterolemia, show similar injection site reactions as mipomersen." (PMID 34357325, 2021). "To date, only two monoclonal antibodies targeting PCSK9 are available for treating hypercholesterolemia: evolocumab and alirocumab." (PMID 33834043, 2021). "Monogenic forms of hypercholesterolaemia have implicated key genes in the LDL-cholesterol transport pathway, including PCSK9, with PCSK9 monoclonal antibodies evolocumab and alirocumab now indicated for treatment of common hyperlipidaemia." (PMID 33836063, 2021). "The PCSK9 gene also undergoes gain-of-function mutations (GOF), that usually result in hypercholesterolaemia causing accelerated vascular aging and CVDs." (PMID 34356856, 2021). "Soon after the discovery of PCSK9 as a molecule with a function in lipid metabolism, there was a surge in interest to develop therapies to target its pathway as a treatment for hypercholesterolemia." (PMID 34070931, 2021). "The discovery of proprotein convertase subtilisin-like kexin type 9 (PCSK9) was a possible breakthrough in tackling hypercholesterolemia." (PMID 34731223, 2021). "PCSK9 has been explored as an attractive therapeutic target for hypercholesterolemia and atherosclerosis." (PMID 33895138, 2021).